AFP (alpha fetoprotein)
Diseases named in the same sentence as AFP in open-access papers (continued):
Sharing a sentence is not in itself a finding about the gene and the disease.
tumor (continued). "The results of subgroup analysis suggested that when patients with tumor located in the adjacent two segments, multiple tumors, maximum tumor size larger than 10 cm, preoperative AFP ≥400 ng/ml, HBV DNA >1000 IU/ml, and margin width ≤2 cm were more inclined to recommend LH." (PMID 33932132, 2021). "High NET1 expression was found to be associated with large tumor size (P = 0.011), high alpha-fetoprotein (AFP) level (P = 0.015), micro metastasis (P = 0.004), portal vein tumor thrombus (PVTT, P = 0.025) and histologic evidence of microvascular invasion (P = 0.025)." (PMID 33839702, 2021). "AFP level has also been proven to be associated with the risk of MVI and tumor differentiation." (PMID 34503212, 2021). "In the absence of correlation at AUC>0.75, each tumor marker makes additional contribution to the diagnostic efficiency without duplicating AFP indices." (PMID 34513063, 2021). "We also noticed that GAPR was significantly positively correlated with the tumor size in AFP‐NHCC." (PMID 34145988, 2021). "AFP was assumed to be adverse to tumor suppression due to inhibiting lymphocyte transformation." (PMID 33912455, 2021). "Of course, whether the function of AFP-specific T lymphocytes can be efficiently activated in vivo to target AFP-expressing tumour cells needs to be further explored." (PMID 34496797, 2021). "Subsequently, the addition of biological markers, predominantly AFP serum levels, to the morphological characteristics of the tumor emerged as the more solid and reproducible criteria for patient selection beyond the MC for LT, assuring excellent post-LT outcomes." (PMID 34501381, 2021). "Lower rates of TERTp mutations, instead, were observed in the proliferative HCC class, arising in livers characterized by longer telomeres, categorized as more aggressive tumours with poor histological differentiation, high vascular invasion, and increased levels of AFP." (PMID 34359670, 2021). "In a study including 42 patients with unresectable primary liver cancer, ctDNA could correlate more closely with the tumor load and could predict treatment efficacy with higher sensitivity, compared to AFP or imaging." (PMID 34503144, 2021). "The Univariate Cox Regression analysis showed that tumor size (P = 0.033), TNM stage (P = 0.005), serum AFP level (P = 0.036), tumor differentiation (P = 0.008), vascular invasion (P = 0.048), and high expression of CTSA (P = 0.039) were risk factors affecting OS." (PMID 34272452, 2021). "Multivariate regression analysis of these factors showed that current smoking, albumin, prealbumin, AFP, varicose veins of gastric fundus, BDTT, macrovascular invasion, MVI, tumor number, and maximal tumor diameter as independent risk factors of survival of patients with HCC." (PMID 34976789, 2021). "Previous studies have reported that tumor markers, such as AFP, CEA, and CA 19-9, have no diagnostic value with respect to primary hepatic NEC." (PMID 34727269, 2021). "Following serum tumor makers were tested, including carbohydrate antigen-125 (CA-125):61.87 μl/ml (0.00–35.00 μl/ml), α-fetoprotein (AFP):9.40 ng/ml (0.00–7.00 ng/ml), carcinoembryonic antigen (CEA):1.61 ng/ml (0.00–4.30 ng/ml), human chorionic gonadotrophin:1.88 mIU/ml (0.00–3.00 mIU/ml)." (PMID 33578605, 2021). "First, some recognized factors, such as tumor size, AFP, and vascular invasion, are not independent risk factors for OS and PFS in patients with HCC." (PMID 34790226, 2021). "AFP peptide vaccine showed good anti-tumor activity in the treatment of HCC." (PMID 34513678, 2021). "Furthermore, so-called “classical” serum tumor markers (alpha fetoprotein (AFP), human chorionic gonadotropin (HCG), and lactate dehydrogenase (LDH)) are commonly ordered." (PMID 33800799, 2021).
tumor (continued). "After adjusting for AFP levels and tumor size in the Cox multivariable model, the initial dosage of 120 or 160 mg/d (HR = 0.216, 95% CI 0.061–0.765, P = 0.018) and patients achieving PD (HR = 5.607, 95% CI 1.896–16.578, P = 0.002) were independently associated with PFS." (PMID 34670512, 2021). "Four tumor biomarkers, including AFP, CEA, CA125 and CA199, are widely used in clinical practice." (PMID 33691685, 2021). "Additionally, AFP > 200 ng/mL (p = 0.002), ALBI grade II/III (p = 0.002), and tumor stage (p < 0.001) were independent risk factors for poor OS." (PMID 34666694, 2021). "Alpha-fetoprotein (AFP) is a tumor marker commonly used for diagnosing patients with HCC." (PMID 34745328, 2021). "However, its sensitivity and specificity in monitoring efficacy is low, and its recurrence diagnostic efficacy is similar to clinical tumor biomarkers such as CEA and AFP." (PMID 33562269, 2021). "Of note, lymphovascular invasion and tumor differentiation can only be ascertained after resection and, thus, serum AFP may act as a surrogate of these unfavorable characteristics in the pre-operative setting." (PMID 33670174, 2021). "Furthermore, the only variable independently related to tumour recurrence was an AFP level higher than 30 ng/dL." (PMID 34944957, 2021). "Our work indicated that MVI classification, HBeAg status, preoperative blood AFP level, number of tumors, largest tumor diameter, the status of satellite nodules and serosal invasion were independent risk factors for early-relapse in HCC patients with MVI after R0 resection." (PMID 34229698, 2021). "A new type of inorganic mixed oxide, LaMnO3, with a perovskite crystal structure was recently employed for designing an assay for simultaneous detection of multiple tumor markers, such as the alpha fetoprotein (AFP), carcinoembryonic antigen (CEA), and prostate specific antigen (PSA)." (PMID 35009703, 2021). "AFP expression level in tumor tissue was not strictly associated with serum AFP or hepatoid differentiation." (PMID 33996549, 2021). "In the multivariate regression model I, AFP levels higher than 400 ng/mL were found to be the best predictors for positive MVI with an odds ratio (OR) value of 5.12, followed by CEUS LR-M (OR=3.80), 20 ng/mL<AFP level<400 ng/mL (OR=3.11) and tumor size larger than 30 mm (OR=2.86)." (PMID 34307168, 2021). "Since many tumor cells express AFPRs and these cells can take up AFP and exert malignant effects, the elucidation of AFPRs structure and function will help expand academic understanding of cancer cell transformation, proliferation, progression, migration and invasion." (PMID 33718192, 2021). "In LDLT, more liberal cutoffs on tumor size, number and AFP are used." (PMID 34181327, 2021). "She tested negative for hepatitis B surface antigen and hepatitis C virus antibody; levels of tumor markers, alpha-fetoprotein, carcinoembryonic antigen, cancer antigen 19–9, neuron-specific enolase (NSE), and progastrin-releasing peptide (ProGRP) were within the standard values." (PMID 33566306, 2021). "AFP, tumor size, tumor differentiation, tumor number, and MVI were included into the nomogram." (PMID 34745962, 2021). "Similarly, variable tumor size, number and AFP level cutoffs were used in the Metro ticket 2.0 model proposed by the Milan group." (PMID 34295467, 2021). "Thus, serum AFP is also a useful tumor biomarker for assessment for the therapeutic effect and predictions of recurrence, residue, and metastasis during the follow-up period in patients with YST." (PMID 33663127, 2021). "Serum alpha fetoprotein (AFP), a marker of tumor burden, was measured." (PMID 33580090, 2021). "Recently, a retrospective multicentre study in China investigated the endpoint of downstaging the Hangzhou Criteria (HC): (a) reduction in total tumour diameter ≤ 8 cm or (b) total tumour diameter > 8 cm with grade I or II tumour differentiation but AFP level ≤ 400 ng/mL." (PMID 34944957, 2021).
tumor (continued). "The other tumor biomarkers (CA125, CA15-3, SCC-Ag, AFP, and CEA) had poor diagnostic efficacy." (PMID 34527571, 2021). "In addition, first we found that total bilirubin was also a significant predictive factor for MVI when integrated the tumor diameter and AFP." (PMID 34234239, 2021). "AFP (alpha‐fetoprotein) is the most widely used blood serum tumor marker for the detection of HCC." (PMID 34145988, 2021). "The study indicated that alpha-fetoprotein (AFP), a specific tumor marker, was significantly decreased in HCC patients after Maytenus compound treatment." (PMID 33976742, 2021). "Serum tumor markers, such as alpha fetoprotein (AFP), human chorionic gonadotropin (hCG), and lactose dehydrogenase (LDH), are widely applied clinically and effective in the diagnosis, staging, risk stratification, treatment, and evaluation of patients’ response to chemotherapy in TGCT." (PMID 33777092, 2021). "This study demonstrated that the prediction of tumour recurrence could be significantly improved by incorporating AFP in the selection criteria." (PMID 34944957, 2021). "These facts suggest that the tumor cells apparently produced AFP." (PMID 33913027, 2021). "Blood AFP level might be positively related to the diameter of tumor in HCC patients, and the presence of tumor enlargement is a predictive factor for poor prognosis." (PMID 34229698, 2021). "Furthermore, NET1 expression was closely related to some clinical features of HCC cases, including AFP, tumor size, micro metastasis, microvascular invasion and PVTT, which are the most important clinical markers in the progression of HCC." (PMID 33839702, 2021). "Fourth, AFP, albumin, and initial tumor size independently predicted HCC TGR." (PMID 34966854, 2021). "Among the tumor markers, AFP was significantly elevated (12,913.0 μg/L)." (PMID 35187075, 2021). "Treatment with TACE-iodine-125 provided a better OS in the subgroups of male, ECOG = 0, type of Vp1 + Vp2, single tumor, size > 5 cm, and AFP > 400 ng/mL, compared OS of the subgroups of female, ECOG = 1 + 2, type of VP3, multiple tumors, size ≤5 cm, and AFP ≤ 400 ng/mL." (PMID 34521375, 2021). "Compared with traditional tumor biomarkers (such as AFP and DCP in HCC), the analytes assayed as liquid biopsy bear high sensitivity, specificity, and could be detected in dynamical manner, enabling consecutive tumor progression warning." (PMID 34729120, 2021). "A common thread that links the various selection criteria adopted in different countries is to consider the morphological characteristics of the tumor (number and size of nodules) and the values of some biological markers, mainly AFP, as main determinants of the selection process." (PMID 34501381, 2021). "Tumor markers, such as alpha-fetoprotein (AFP) and beta-hCG, may help guide the decision to operate rather than observing." (PMID 33806632, 2021). "In addition, CSCs-derived exosomes effectively increase the levels of serum tumor markers (AFP and GGT) and liver enzymes (ALT, AST and ALP) in DEN-induced HCC rats, as well as increasing the number of metastatic of cancer nodules." (PMID 33869059, 2021). "For small tumor (< 2 cm), the model had an AUC of 0.95 compared to AFP (0.72)." (PMID 34714420, 2021). "And, there were some tumor cells positive for AFP in immunohistochemical staining." (PMID 33913027, 2021). "Associations between tumour-related factors and both PIVKA-II and AFP were assessed." (PMID 34853657, 2021). "The NCDB does not capture some clinically important data fields, such as staging of liver tumors according to the Children’s Oncology Group or pretreatment extent of disease, chemotherapy regimen, alpha-fetoprotein level, and response of the tumor to chemotherapy." (PMID 34208030, 2021).
tumor (continued). "Univariate Cox regression analysis showed that among the candidate variables, five variables, including BCLC stage, tumour size (≥5 cm vs. <5 cm), AFP (≥200 ng/ml vs. <200 ng/ml), interval (<14 days vs. ≥14 days) and radiomics signature (high-risk vs. low-risk), had p values <0.05." (PMID 34532340, 2021). "Interestingly, low SIRT1 levels were detected in 70 cirrhotic HCC patients carrying the rs7895833 variant, and SIRT1 reduction was inversely correlated with high AFP, Child–Pugh score and tumor stage." (PMID 33920670, 2021). "Serum tumor markers, including alpha-fetoprotein, were in the normal range." (PMID 33896422, 2021). "However, the survival ability of tumour cells at this stage has exceeded the killing ability of this antitumour immunity, and solitary AFP-specific T cells cannot control tumour progression." (PMID 34496797, 2021). "In addition, the cancer markers alpha-fetoprotein, tumor marker, S (0.78%) and epidermal growth factor receptor (EGFR) (1.56) were found to be the main contributors for the prediction of cancers of the liver and bronchus and lung." (PMID 34032581, 2021). "Largest tumor diameter, tumor number, AFP and neutrophil to lymphocyte ratio were assessed." (PMID 34295467, 2021). "In addition, the data suggested that surgeons should consider pre-operative AFP levels to optimize patient selection, especially when considering a major resection for high tumor burden disease." (PMID 33670174, 2021). "Furthermore, we found that the high expression of UCA1 is positively correlated with serum AFP, tumor size, and distant metastasis, and predicts poor prognosis." (PMID 33565716, 2021). "The mean baseline alpha-fetoprotein (AFP) tumor marker was 263 ± 526 ng/mL." (PMID 34336728, 2021). "AST, GGT, TB, AFP and tumor diameter were selected using LASSO binary logistic regression analysis." (PMID 34234239, 2021). "Further research is needed to address whether overexpression of SOX2 in HCC occurs before that of other tumor markers, in particular of AFP." (PMID 34436030, 2021). "Additionally, percutaneous biopsy is necessary to diagnose tumor unresectability, and determine levels of serum AFP and HCG levels." (PMID 34713845, 2021). "Tumor size, fibrosis score and AFP varied greatly with different stages." (PMID 34887446, 2021). "Reduced expression of circTRIM33-12 was related to larger tumor size, multiple tumors, encapsulation invasion, and MVI, as well as elevated AFP levels, while decreased expression of cSMARCA5 is closely related to poor tumor differentiation, advanced tumor stage, larger tumor size, and MVI." (PMID 34540684, 2021). "Overall, the AFP, Child–Pugh score, and tumor size may increase with the progression of the disease in both the general population and the independent HIV population." (PMID 33436856, 2021). "AFP is a standard tumor marker for diagnosis and treatment evaluation in YSTs15." (PMID 34117242, 2021). "Both tumor morphology (i.e., tumor burden) and tumor-specific biomarkers (i.e., serum AFP) may be important when assessing the prognosis of patients who undergo resection for HCC." (PMID 33670174, 2021). "The model incorporated tumor size and number, alpha fetoprotein (AFP) level (ng/ml), protein induced by vitamin K absence (PIVKA) level (mAU/ml), lymphocyte count (/ul), serum albumin level (g/dl), and ascites, and a nomogram was developed to predict patient survival." (PMID 33903282, 2021). "Among 322 GC patients followed-up for 128 months, the tumor markers alpha fetoprotein, carcinoembryonic antigen, carbohydrate antigen 19-9 (CA19-9), carbohydrate antigen 15-3 and carbohydrate antigen 72-4 of 168 patients were detected before surgery, and their impact on survival was analyzed." (PMID 34889247, 2021). "Alpha-fetoprotein (AFP) and protein induced by vitamin K absence or antagonist-II (PIVKA-II) are common diagnostic and prognostic biomarkers for HCC that have a positive correlation with tumor burden." (PMID 34218801, 2021).
tumor (continued). "Furthermore, we demonstrated that the levels of miR-146a can distinguish between cirrhotic patients with and without HCC with a ROC/AUC of 0.80, comparable to the established tumor marker AFP (ROC/AUC: 0.83)." (PMID 34069692, 2021). "Additionally, its sensitivity declines significantly in detecting early HCC because elevated AFP level is typically correlated with large tumor size, poor tumor differentiation and presence of vascular invasion." (PMID 34045534, 2021). "Among the tumor markers, serum AFP was elevated (816.2 ng/mL)." (PMID 33607799, 2021). "Indeed, following the surgical resection of the primary tumors, intensive screening was usually applied using AFP levels and CT or MRI, and the recurring tumors were usually detected in the early stage, with less than 3 cm tumor size." (PMID 34212527, 2021). "In addition to prognostication and possible therapeutic impact, another important reason to recognize AFP+ EC is the post-operative surveillance: serum AFP can be a useful tumor marker for patients with this disease." (PMID 34977100, 2021). "Survival analysis and Cox proportional hazards regression model showed that overall survival was lower in HCC patients with high ACLY expression; AFP level, TNM staging, tumour size and ACLY expression level were independent risk factors affecting their overall survival." (PMID 33393219, 2021). "Further analyses of the correlations between the breadth of the T cell response, i.e., the number of CTA, SALL4 and AFP being recognized, and the tumour stage and other tumour characteristics were performed according to the distinct profile of the tumour antigen-specific T cell response." (PMID 34496797, 2021). "AFP levels were confirmed as a sensitive readout for HCC tumor development after tumors were harvested and weighed on the day of sacrifice and a strong correlation (R2 = 0.706) was observed between individual animal plasma AFP levels and tumor weights." (PMID 33747358, 2021). "In other words, in patients with tumor lesions of smaller diameter and lower AFP levels who undergo curative treatment, DAA use may be more efficacious for suppressing recurrence, including unexpected recurrence, compared with DAA non-use." (PMID 33278003, 2021). "However, the proportions of patients with AFP > 400 ng/mL, microvascular invasion, and moderate/poor tumor differentiation were higher in the > 5 cm group than in the ≤ 5 cm group." (PMID 34381132, 2021). "Notably, INT-1B3 treatment resulted in a significant reduction in median AFP levels over time, highlighting its anti-tumor activity in the Hep3B model." (PMID 33747358, 2021). "AFP was initially found to be taken up by fetal cells, and later studies found that muscle tumor cells also internalize exogenous AFP." (PMID 33898423, 2021). "We assessed the serum levels of several tumor markers, AFP, CA125, and CA19-9." (PMID 34857736, 2021). "Similarly, in another study, two patients with AFP+ tumor treated with an AFP-DNA vaccine followed by an adenovirus immune-boosting exhibited AFP-specific CD4+ and CD8+ T-cell–mediated cytotoxic response." (PMID 34358082, 2021). "CTA- and SALL4-specific T cell responses may be important for controlling HCC in the early stage, whereas AFP-specific T cell responses might be a signature of malignant tumour status in the advanced stage." (PMID 34496797, 2021). "Data from the current retrospective study highlight that both tumor morphology (i.e., tumor burden) and tumor-specific biomarkers (i.e., serum AFP) could be important when assessing the prognosis of patients who undergo resection for HCC." (PMID 33670174, 2021). "The P value of T stage is <0.001, the P value of gender is 0.006, the P value of residual tumor is 0.008, the P value of histologic grade is <0.001, the P value of adjacent hepatic tissue inflammation is 0.011, the P value of AFP is <0.001, and the P value of vascular invasion is 0.028." (PMID 34336727, 2021).